TLR4 (toll like receptor 4)
Diseases named in the same sentence as TLR4 in open-access papers (continued):
Sharing a sentence is not in itself a finding about the gene and the disease.
colitis (482 papers, 2005 to 2026). Inflammation of the colon. "TLR4-deficient (TLR4-/-) mice manifest a heightened susceptibility to DSS-induced colitis, characterized by the dysbiosis of intestinal microbiota and disruption of immune homeostasis." (PMID 41488633, 2025). "Macrophage Tim-3 deficiency exacerbates DSS-induced colitis susceptibility by impairing TLR4/NF-κB signaling, thereby inducing neutrophil necroptosis." (PMID 41150761, 2025). "For example, oxidized PUFAs promote colitis-associated tumorigenesis in murine models through Toll-like receptor 4- and gut microbiota-dependent mechanisms." (PMID 40958322, 2025). "The inhibitory effect of nutritional components in DM on the TLR4/MyD88/NF‐κB pathway likely underlies its ameliorative action against DSS‐induced colitis." (PMID 40994452, 2025). "In recent years, TLR-4 overexpression in inflammatory bowel disease and colitis-associated colorectal cancer has been widely recognized." (PMID 40404908, 2025). "TLR4, a pattern recognition receptor, initiates colitis-associated inflammation upon recognizing intestinal pathogens." (PMID 41517138, 2025). "The potential of ACP as a treatment for liver inflammation linked to colitis is highlighted by its capacity to suppress the TLR4/MyD88/NF-κB pathway in the liver." (PMID 40725052, 2025). "L. plantarum strains (e.g., L15, ELF051) have been shown to suppress NF-κB activation through downregulation of the TLR4/MyD88 axis, reducing pro-inflammatory cytokine expression in murine models of colitis and antibiotic-associated diarrhoea." (PMID 41141596, 2025). "It is also associated with agonists of Toll-like receptors, with Toll-like receptor 4 signaling increasing the risk of colitis and colitis-associated cancer." (PMID 40070479, 2025). "Constitutive epithelial TLR4 activation amplifies inflammatory responses to mucosal injury, contributing to colitis-associated tumorigenesis." (PMID 38930793, 2024). "Inhibition of NF-κB, particularly through targeting the LPS/TLR4/NF-κB pathway, proves to be a promising strategy for preventing colitis-associated carcinogenesis." (PMID 38930793, 2024). "In colitis-associated carcinogenesis, NF-κB activation via the LPS/TLR4 pathway contributes to CAC metastasis." (PMID 38930793, 2024). "The TLR4 signal pathway associated with inflammation has been discovered in many conditions, such as colitis, and intracerebral hemorrhage." (PMID 36748219, 2023). "Conversely, in the murine acute colitis model, TLR4 deficiency caused severe mucosal damage, which was characterized by impaired epithelial proliferation and significant bacterial invasion." (PMID 37191444, 2023). "Another study has revealed rutin and quercetin to be the components of Zanthoxylum bungeanum pericarp extract, which ameliorates experimental colitis through modulating the TLR4 and TLR4-associated pathway." (PMID 36619207, 2022). "Here, we show that intestinal microbiota dysbiosis caused by the loss of TLR4 gives rise to imbalanced immune responses and an enhanced predisposition to colitis in mice." (PMID 35761415, 2022). "Meanwhile, neutrophils, macrophages and basophils exclusively infiltrated and TLR4 signaling was activated in the colon of AKR1B8 deficient mice with acute colitis induced by DSS at 1.5%." (PMID 36518763, 2022). "Modified citrus pectin downregulated the expression of TLR4 in rats with myocardial fibrosis, and an oligogalactan from apple pectin effectively reduced the elevated levels of TLR4 in a mouse model of colitis-associated colon cancer." (PMID 35745651, 2022). "Previous studies have indicated that TLR4 deficiency renders mice susceptible to DSS-induced colitis, which is associated with impaired intestinal barrier function and changes in the inflammatory cytokine profile." (PMID 35761415, 2022). "Our results indicated that resident intestinal bacteria were required for the enhanced susceptibility of TLR4−/− mice to colitis." (PMID 35761415, 2022).
colitis (continued). "Prior studies have demonstrated that TLR4-deficient mice develop severe DSS-induced colitis, which is linked to impaired intestinal barrier function and changes in the inflammatory cytokine profile." (PMID 35761415, 2022). "Despite this, an HP microbiome had an exacerbated pro-inflammatory potential via increased production of microbiota EV that can activate TLR4, which was associated with exacerbated colitis compared to both HC- and HF-fed mice." (PMID 35896537, 2022). "The disrupted epithelial barrier allows proinflammatory bacteria to pass through and cause LPS/TLR4/NF-κB signaling pathway mediated macrophage activation, thereby promoting the progression of colitis." (PMID 36313077, 2022). "Inhibition of the TLR4/NF-κB pathway is associated with an alleviative effect on DSS-elicited colitis." (PMID 36619207, 2022). "We observed that TLR4−/− mice developed severe colitis, as evidenced by increased weight loss, decreased survival rate, a higher DAI score, and a shortened colon length." (PMID 35761415, 2022). "Excessive activation of TLR4 in intestinal epithelial cells induces GM disturbance and increased susceptibility to colitis." (PMID 36310616, 2022). "In this study, we investigated the protective role of TLR4 in the shaping of colonic bacterial compositions and microbiota-associated immunity against colon inflammation." (PMID 35761415, 2022). "As expected, A. muciniphila supplementation markedly ameliorated colitis not only in the WT genotype but also in the TLR4-deficient genotype in our study." (PMID 35761415, 2022). "In recent years, considerable attention has been focused on the regulation of TLR4 signaling in the context of colitis-associated tumorigenesis." (PMID 34479599, 2021). "In contrast, several other studies highlighted the pathogenic function of TLR4 signaling in DSS colitis." (PMID 34124086, 2021). "In particular, an increase of E. Coli in the microbiota was associated with less severe colitis in TLR4 deficient mice." (PMID 34124086, 2021). "Another study reported that TLR4 activated the inflammatory pathways and promoted the development of colitis-associated colorectal tumors." (PMID 34385421, 2021). "Overall, our results strengthen the importance of TLR4 activation during intestinal inflammation for the development of colitis-associated colon cancer." (PMID 34025672, 2021). "For further validating SHD targets in C. albicans-associated colitis, key TLR4-NF-κB and PI3K-Akt pathway effectors were examined." (PMID 34376226, 2021). "Numerous evidence disclosed that the activation of the TLR4/MYD88/NF-κB signaling pathway is associated with the pathogenesis of colitis." (PMID 34683415, 2021). "The modulating role has also been demonstrated for black tea extract, which reduces physiological manifestations of colitis, regulates the TLR4/MyD88/NF-κB pathway, and causes a selective modulation of the microbiota in chemical-induced colitis in mice." (PMID 34200833, 2021). "Consistently, Tlr4- and Myd88-KO mice are more susceptible to infection and colitis than WT mice due to increased bacterial translocation and decreased AMP expression." (PMID 33767714, 2021). "To investigate the underlying relevance of pinocembrin on TLR4/NF-κB signaling during DSS-induced colitis, we evaluated the influence of pinocembrin on the activation of TLR4 and the phosphorylation of p65 by immunoblotting." (PMID 32687156, 2020). "A study has confirmed that MAL serves as a bridge between TLR2/TLR4- and MyD88-mediated signaling to orchestrate downstream inflammatory responses and regulate intestinal homeostasis and colitis-associated colorectal cancer in mice." (PMID 32099532, 2020). "We found that preserved TLR4 signaling was important for severe colitis induction in HSD-fed mice as TLR4-deficient mice showed milder signs of colitis when compared with wild-type mice." (PMID 33339337, 2020).
colitis (continued). "The induction of colitis in Toll-like receptor 4 (TLR4)-deficient HSD-fed mice led to significantly milder colitis than in wild-type mice." (PMID 33339337, 2020). "In conclusion, the present study successfully indicated HnAb ameliorated colonic inflammation in DSS-induced colitis and TLR4 deficiency enhanced the protective effect in some aspects." (PMID 33193406, 2020). "HnAb was administered via intraperitoneal injection to TLR4 deficient mice and their wild-type littermates, both being induced to colitis with DSS." (PMID 33193406, 2020). "Colitis in HSD-fed TLR4-deficient mice was markedly milder and almost equally severe as in CD-fed mice." (PMID 33339337, 2020). "Our results are also consistent with those of a previous study that TLR4 KO mice are more susceptible to colitis than WT mice." (PMID 32042047, 2020). "Together, these results showed a critical role for the TLR4-mediated immune response in the tumorigenesis of colitis-associated CRC." (PMID 31523496, 2019). "This contradicts previous reports on curcumin’s anti-inflammatory effects in colitis, which had been linked to the attenuation of the TLR4/MyD88/NF-κB inflammatory pathway by inhibiting TLR4 homodimerization and decreasing MyD88 expression." (PMID 31026259, 2019). "The colons of mice deficient in corticotropin-releasing factor express less TLR4 mRNA and develop a more severe colitis in response to DSS." (PMID 29515999, 2018). "Results from transgenic villin TLR4 mice suggest that TLR4 can modulate the susceptibility of DSS-induced colitis, which can be transmissible by gut microbiota." (PMID 30537997, 2018). "Overexpression of TLR4 results in the activation of β-catenin and increased colitis-associated cancer development, whereas the inhibition of TLR4 expression is shown to protect against CRC." (PMID 29474889, 2018). "Under conditions of injury, however, MyD88-, TLR2-, and TLR4-deficient mice show increased susceptibility to dextran sodium sulfate (DSS)-induced colitis." (PMID 29354132, 2017). "Under chronic intestinal inflammatory conditions including IL10−/− colitis MDR PA-association results in well-orchestrated TLR4-dependent immune responses both in intestinal and extra-intestinal compartments." (PMID 29151895, 2017). "It has been found that TLR4/MyD88 pathway can promote the development of colitis-associated colorectal tumors." (PMID 28769820, 2017). "It has been reported that high protein abundance of TLR4 in mouse intestinal epithelium induces colitis-associated tumor development, whereas TLR4 knock-out mice are protected against this disease." (PMID 28423670, 2017). "Antibiotic treatment decreases the incidence of colorectal cancer tumorigenesis and TLR4 inhibitor attenuates the susceptibility of CK8+/− mice to DSS-induced colitis." (PMID 29228570, 2017). "Further evidence for the contribution of TLR signaling to the development of sporadic cancer, and colitis-associated cancer, stemmed from the use of TLR4-deficient mice that were protected against tumorigenesis following azoxymethane (AOM) and DSS treatment." (PMID 29354132, 2017). "Blocking TLR4 can prevent the progress of DSS-induced colitis, and TLR4 deficient mice were markedly protected from colon carcinogenesis." (PMID 27105524, 2016). "Although villin-TLR4 mice are more susceptible to colitis, the microbial changes observed in these mice are the direct opposite of what is normally observed in IBD patients." (PMID 26755160, 2016). "On the other hand, we have previously reported that mice expressing a constitutively active form of TLR4 in the intestinal epithelium (villin-TLR4 mice) exhibit increased susceptibility to chemically induced colitis." (PMID 26755160, 2016). "In these studies TLR4 deficient mice are reported to develop severe DSS-induced colitis suggesting that TLR4 stimulation in intestinal mucosa by gut microflora results in secretion of factors that promote epithelial restitution after injury." (PMID 25793763, 2015).
colitis (continued). "Our laboratory has studied the role of TLR4 in intestinal inflammation and colitis-associated neoplasia, supporting the function of TLR4 as a tumor promoter in human tissue and murine models." (PMID 24887394, 2014). "TLR4 is overexpressed in individuals with colitis-associated CRC, and constitutive activation of TLR4 enhances cancer development in mouse models of this disease." (PMID 25256712, 2014). "Mice deficient for the murine DC-SIGN homologue SIGNR1 exhibited a reduced susceptibility to experimental colitis since SIGNR1 acts synergistically with TLR4 in the initiation of an inflammatory response upon LPS binding by TLR4." (PMID 25068517, 2014). "The intermediary step of TLR4-mediated PI3K activation complements data demonstrating the role of PI3K in stem cell activation in colitis-associated neoplasia." (PMID 23691015, 2013). "We have previously shown that the AOM-DSS model of colitis-associated cancer is characterized by increased epithelial TLR4 expression; thus it is possible that TLR4 is one of the mediators of PI3K activation seen in CAC." (PMID 23691015, 2013). "Further support for TLR4 signalling in T cells has been reported in a model of colitis, where TLR4/IL-10-deficient T cells were more pathogenic, compared with IL-10-deficent cells." (PMID 23345540, 2013). "When the epithelial TLR4 signaling pathway was blocked in WT mice with colitis-associated tumors, there were fewer colonic polyps." (PMID 24696788, 2012). "TLR4 deficiency makes the mouse susceptible to Dextran sulfate-induced colitis and feeding LPS to normal mice provides protection against DSS-induced colitis." (PMID 22570785, 2012). "Transgenic murine models of colitis with elevated epithelial TLR4 developed severe acute inflammation, greater colitis-associated neoplasia, and elevated levels of inflammatory and pro-oncogenic factors (TNFα, COX-2, PGE-2) versus wild type (WT) mice." (PMID 24696788, 2012). "It has been demonstrated that endotoxemia, colitis, and other inflammatory responses are associated with LPS-induced TLR4 expression." (PMID 23056598, 2012). "TLR4 seems to promote the development of colitis-associated colorectal tumors, and mice deficient in TLR4 are markedly protected against the development of neoplasia." (PMID 22110526, 2011). "TLR4 expression is upregulated in colitis-associated cancer lesions from patients with ulcerative colitis but not in the surrounding tissue." (PMID 22110526, 2011). "Toll-like receptor 4 signalling activation seems to promote the development of colitis-associated cancer by mechanisms including enhanced Cox-2 expression and increased EGFR signalling." (PMID 20145615, 2010). "For example, PAMP-sensing by intestinal epithelial cells has been reported to induce the expression of bactericidal and barrier-enhancing mediators, and deficiency in TLR2, TLR4 or MyD88 was shown to result in increased mortality following DSS-induced colitis." (PMID 20161736, 2010). "Additionally, TLR4 inhibition has been shown to mitigate inflammatory cytokine production and tumor-promoting effects in colitis-associated colon cancer." (PMID 40559922, 2025). "The experiments results showed that ATF may inhibit the occurrence of colitis phenomena, including weight loss, diarrhea, blood in stool, and colon shortening in UC mice by modulating the microbiota-LPS/TLR4/NF-κB/NLRP3 signaling axis." (PMID 40130239, 2025). "TLR4, MyD88, and NF-κB are key genes in the TLR4/NF-κB pathway associated with colitis." (PMID 40862149, 2025). "A substantial number of studies have confirmed that the TLR-4/MyD88 signal can cause excessive cell proliferation, thereby promoting colitis-associated colorectal carcinogenesis through the cyclooxygenase 2, epidermal growth factor receptor, and β-catenin-dependent pathway." (PMID 40404908, 2025).
colitis (continued). "Similarly, recent findings have shown that the TLR4/MyD88 signaling pathway is strongly linked with the inflammatory response in the colitis mouse model and fulfills a crucial role in the pathogenesis of colitis." (PMID 38611304, 2024). "TLR4-deficient mice were protected from DSS-induced colitis." (PMID 38928791, 2024). "UC patients show increased expression and constitutive activation of toll-like receptor 4 and nuclear factor kappa B (TLR4/NF-κB) in colon epithelial cells that may progress into colitis associated cancer." (PMID 37509705, 2023). "The abundance of Akk is decreased in the fecal matter and TLR4 gene expression is upregulated in the intestinal epithelia of patients with UC; these are negatively related to colitis risk, which implies that TLR4 may participate in the development of UC." (PMID 36835309, 2023). "Experimental data have confirmed that TLR4-deficient mice have a decreased level of intestinal inflammation and TLR4 deficiency may prevent colitis-associated neoplasia." (PMID 37998389, 2023). "However, a study on myeloid-cell-lineage-restricted ATX knockout mice showed that ATX deficiency impairs Toll-like receptor 4 (TLR4)-mediated responses in macrophages and hampers the innate immune response, leading to the accelerated development of colitis." (PMID 37569902, 2023). "Other evidence has shown that TLR4 may promote the development of colitis-associated tumors and it may also be associated with metastasis in CRC." (PMID 37998389, 2023). "Using knock-in mice engineered to express the murine homologs of these human TLR4 mutations (“TLR4-SNP” mice), we have shown that TLR4-SNP mice develop significantly more severe colitis induced by dextran sodium sulfate (DSS) than wild-type (WT) mice, similar to IBD in humans expressing these SNPs." (PMID 37768050, 2023). "Since LPS can stimulate TLR4, which leads to initial immune responses in enterocytes, the role of TLR4 mediating the development of colitis-associated tumorigenesis has been established in the aspects of enhancing direct recruitment of NF-κB and the large increase in cytokines." (PMID 37200915, 2023). "Additionally, we found that colitis is associated with meaningfully increase in gene expression of inflammatory cytokines including TLR4, TNF-α and IL-1β." (PMID 35432569, 2022). "We investigated whether the different susceptibilities to colitis between wild-type (WT) and TLR4−/− mice were gut microbiota-dependent and aimed to identify the potential immunity modulation mechanism." (PMID 35761415, 2022). "Genetic deletion of TLR4 has drastic consequences on the structure and composition of the intestinal microbial communities, leading to a shift towards a proinflammatory configuration that drives enhanced susceptibility and vulnerability to colitis." (PMID 35761415, 2022). "In addition, the production of pro-inflammatory cytokines is blocked and symptoms of colitis are ameliorated in TLR4-deficient mice." (PMID 36176442, 2022). "Given the protection of inhibited macrophage polarization against DSS-induced colitis damage, we further conjectured whether the specific pathway by which CJ improves UC by mediating the TLR4-NF-κB/MAPK pathway is associated with macrophage polarization." (PMID 36619207, 2022). "TLR4−/− mice experienced enhanced susceptibility to DSS-induced colitis." (PMID 35761415, 2022). "This may also underline the influence of different TLR4 measurement techniques or relies on the differences in the application of DSS to induce colitis." (PMID 34025672, 2021). "It is confirmed that TLR4 signaling is critical for colon carcinogenesis in colitis, and the inhibition of TLR4 signaling may be useful for protecting against colitis or colitis-associated cancer." (PMID 34684320, 2021). "Given that TLR4 signaling is also involved in intestinal homeostasis and its activation may cause chronic inflammation, we aimed to investigate the role of TLR4 in a murine model of colitis-associated colon cancer (CAC)." (PMID 34025672, 2021).